GDF15 (growth differentiation factor 15)
Diseases named in the same sentence as GDF15 in open-access papers (continued):
Sharing a sentence is not in itself a finding about the gene and the disease.
cardiovascular disease (continued). "Growth differentiation factor 15 (GDF‐15) is a transforming growth factor‐β that is upregulated in a number of conditions including cardiovascular disease." (PMID 39822053, 2025). "GDF15 has emerged as a promising biomarker for cardiovascular disease, attracting increasing research interest in recent years." (PMID 40806859, 2025). "Although the specific cell types responsible for this elevation of GDF15 level remain elusive, heart-resident macrophages are likely involved and this involvement has been demonstrated to influence the progression of cardiovascular diseases." (PMID 40837873, 2025). "The mature-form GDF15 is released from different tissues to the bloodstream as a 25 kDa homodimer in response to different stresses, such as metabolic disorders and cardiovascular diseases, among other pathological conditions." (PMID 40076667, 2025). "Growth differentiation factor 15 (GDF15) is a stress-responsive cytokine that has been studied extensively in cardiovascular disease, but its investigation in PAD remains limited." (PMID 40806859, 2025). "The increased concentrations of preoperative hs-cTnT, NT-proBNP, and GDF-15 in patients with high preoperative IL-6 suggest the presence of subclinical cardiovascular disease." (PMID 40491666, 2025). "Authors have proposed the new biomarker growth differentiation factor 15 (GDF-15) that has predictive power in several scenarios involving cardiovascular disease." (PMID 40561273, 2025). "The expression of GDF15 reflected cellular and mitochondrial stress, which increases with aging and the presence of chronic inflammatory diseases, including metabolic and cardiovascular disorders." (PMID 38275413, 2024). "Growth/differentiation factor-15 (GDF15) is considered an unfavourable prognostic biomarker for cardiovascular disease in clinical data, while experimental studies suggest it has cardioprotective potential." (PMID 38839839, 2024). "Growth differentiation factor 15 (GDF15) has emerged as a promising biomarker in cerebro-cardiovascular disease, particularly in acute and chronic inflammatory stress situations." (PMID 39008451, 2024). "Galectin-3 also has potential in cardiovascular diseases as its levels can predict the severity of coronary slow flow phenomenon in conjunction with GDF-15." (PMID 39328401, 2024). "They suggested using 1500 pg/mL GDF15 as a baseline to assess the presence of cardiovascular disease." (PMID 37093513, 2024). "GDF15 is currently considered as a biomarker of cardiovascular diseases and even as a predictor of disease progression and mortality." (PMID 38791371, 2024). "Studies have shown that, as an important cardiovascular protective factor, GDF-15 is closely related to the diagnosis and prognosis of many cardiovascular diseases." (PMID 37288264, 2023). "Measurements were performed using the Proseek Multiplex Cardiovascular disease panels (Olink Proteomics AB) and validated using the Elecsys GDF-15 electrochemiluminescence immunoassay on a Cobas E801 analyzer (Roche Diagnostics)." (PMID 37008733, 2023). "Growth differentiation factor 15 is a prognostic biomarker in multiple disease entities, including cardiovascular disease." (PMID 37008733, 2023). "Elevated GDF-15 has been associated to increased risk of death and detrimental occurrences after ACS in STEMI patients, confirming its potential as a biomarker for cardiovascular disease." (PMID 36864452, 2023). "Studies have shown that GDF-15, as an important cardiovascular protective factor, is closely related to the diagnosis and prognosis of many cardiovascular diseases." (PMID 37288264, 2023). "Stress- and inflammation-induced growth differentiation factor-15 (GDF-15) isproposed as a biomarker for mortality and disease progression in patients withatherosclerosis and/or cardiovascular disease (CVD)." (PMID 39077481, 2023).
cardiovascular disease (continued). "Among the 10 cardiovascular disease markers tested, 7 showed significant differences between groups (D-dimer, GDF-15, myoglobin, sICAM-1, MPO, P-selectin and lipocalin-2/NGAL)." (PMID 36163447, 2022). "Among cardiovascular diseases, there were biomarkers with differences between the groups, with D-dimer, GDF-15, and sICAM-1 higher in the S group." (PMID 36163447, 2022). "Growth differentiation factor‐15 (GDF‐15) is a member of the transforming growth factor β superfamily, correlated with various stimuli, including cardiovascular disease." (PMID 35334497, 2022). "This within-subjects design allowed us to account for inter-individual variability since GDF15 has shown to be elevated in other contexts, such as neurodegenerative and cardiovascular disease." (PMID 33520124, 2021). "In general, the concentrations of IGFBP7 and GDF-15 were lower than those reported in other studies, focused on patients with cardiovascular disease." (PMID 34217226, 2021). "The mechanisms and prediction of GDF15 in the cardiovascular disease with CKD needs further discussion and study." (PMID 33567936, 2021). "Studies suggest that the increase of serum GDF15 concentration is related to the development and progress of cardiovascular disease." (PMID 34566964, 2021). "The DAN-MONICA (Danish-Multinational MONitoring of trends and determinants in Cardiovascular disease) cohort illustrated the predictive role of repeated blood GDF15 measurement for death due to CHD and the occurrence of HF." (PMID 34445593, 2021). "Are the elevated GDF15 concentrations found in conditions such as ageing and frailty, with chronic renal and cardiovascular diseases playing an active role in the pathogenesis of these disorders?" (PMID 32310257, 2020). "Previous studies emphasizing the association between plasma GDF-15 concentrations and cardiovascular disease have suggested GDF-15 as a potential biomarker for cardiovascular diseases." (PMID 33239667, 2020). "GDF-15 expression is dramatically upregulated in cardiovascular disease, and the incidence of cardiovascular events is positively correlated with the concentration of GDF-15, suggesting its potential value as a disease biomarker." (PMID 32016113, 2020). "Regarding the cardiovascular disease-related proteins, patients on warfarin and rivaroxaban presented similar levels of GDF-15 and both groups higher than controls." (PMID 32793635, 2020). "Compared with DNAm PhenoAge, DNAm GrimAge includes more clinical biomarkers, such as cardiovascular disease related plasma proteins (e.g. C-reactive protein, and growth differentiation factor-15)." (PMID 32561690, 2020). "In the last decade, growth differentiation factor 15 (GDF-15), an inflammatory cytokine released in response to tissue injury, has emerged as a biomarker with prognostic value in cardiovascular diseases and other acute and chronic conditions." (PMID 31624933, 2019). "From the perspective of cardiovascular disease, previous work demonstrates that the peripheral expression of GDF15 is tightly regulated and induced in cardiovascular cell types under specific stress stimuli." (PMID 29967567, 2018). "GDF15, also named as macrophage inhibitor cytokine (MIC-1), is a divergent member of the TGF-β superfamily, and is associated with many diseases including cardiovascular disease and cancer." (PMID 30425709, 2018). "Recent scholarship has called attention to the importance of growth differentiation factor 15 (GDF-15) as a protein biomarker with valuable prognostic utility for predicting adverse outcomes in patients with cardiovascular disease (CVD)." (PMID 29714603, 2018). "In this study, GDF15 was modestly correlated with and additive to CRP in identifying those at risk for cardiovascular disease events." (PMID 29967567, 2018). "In recent years, studies have shown that GDF-15 levels can help in predicting mortality and adverse events in patients with cardiovascular diseases and other diseases." (PMID 28178959, 2017).
cardiovascular disease (continued). "As an emerging biomarker, GDF-15 shows promise because it was found to be increased in early subclinical disease, retaining prognostic utility for cardiovascular disease events and mortality." (PMID 31435501, 2017). "On the one hand, inhibition of GDF-15 has been suggested to dampen inflammatory reactions and cardiovascular diseases." (PMID 29180833, 2017). "Some studies also showed its potential to use GDF-15 as a prognostic marker for therapeutic intervention for different cardiovascular disorders." (PMID 26273671, 2015). "It was concluded that cathepsin S, sopluble CD40 ligand, placental growth factor, and GDF-15 were instructive biomarkers for predicting cardiovascular diseases." (PMID 26273671, 2015). "Although the use of GDF-15 as a biomarker for cardiovascular disease is well established, its therapeutic application is debatable." (PMID 26273671, 2015). "It is a challenge for the scientific community to use GDF-15 information for patient monitoring, clinical decision-making, and replacement of current treatment strategies for diabetic and cardiovascular diseases." (PMID 26273671, 2015). "More intervention studies like AT1 receptor antagonist need to be carried out to bring GDF-15 as a prognostic marker for diabetic and cardiovascular diseases." (PMID 26273671, 2015). "Further research is essential before considering GDF-15 as therapeutic intervention against cardiovascular diseases." (PMID 26273671, 2015). "Our results support the notion that GDF-15 integrates information on several relevant aspects and pathways in cardiovascular disease." (PMID 24839357, 2014). "The prominent antiapoptotic, antihypertrophic, and anti-inflammatory actions of GDF-15 in cardiovascular disease models indicate that this cytokine exerts protective effects in the context of acute cardiovascular injury." (PMID 24839357, 2014). "In cardiovascular disease, much evidence demonstrates that GDF15 is a protective cytokine against multiple stimuli via many signaling pathways including PI3K/Akt, ERK1/2, and SMAD2/3." (PMID 23799024, 2013). "In cardiovascular disease, GDF15 has great potential as a biomarker for prognosis and as a protective cytokine against different stimuli via specific signaling pathways, such as PI3K/Akt, ERK1/2, and SMAD2/3." (PMID 23799024, 2013). "Expression of GDF‐15 is induced under conditions of inflammation and increased GDF‐15 serum levels are suggested as a risk factor for cardiovascular diseases." (PMID 23316317, 2012). "Over the past decade, GDF15 has emerged as a promising biomarker for cardiovascular disease." (PMID 40723863, 2025). "Given these encouraging prognostic insights, further basic and translational studies are needed to elucidate GDF15’s role in cardiovascular disease pathophysiology and to evaluate its viability as a therapeutic target for reducing systemic cardiovascular risk in patients with PAD." (PMID 40723863, 2025). "While the level of GDF15 increased, the level of SBP gradually increased, and GDF15 was positively correlated with SBP (r = 0.274) and UA (r = 0.182) (p < 0.05), which is in line with the fact that GDF15 is associated with cardiovascular disease." (PMID 41497484, 2025). "The fact that GDF-15 may be elevated not only in rhabdomyolysis but also in various comorbidities such as cardiovascular diseases, malignancies, and systemic inflammatory conditions may limit its specificity." (PMID 40731746, 2025). "Moreover, although serum GDF-15 was studied as a biomarker for cardiovascular disease in children, it was found unsuitable for that purpose because of its strong association with kidney function." (PMID 41141543, 2025). "Furthermore, these findings underscore the need for continued basic and translational investigations into the biological mechanisms linking GDF15 to cardiovascular disease pathophysiology." (PMID 40723863, 2025).
cardiovascular disease (continued). "It seems that GDF15 signaling might attempt to prevent the vascular dysfunction underpinning many cardiovascular diseases." (PMID 39643709, 2024). "They showed that GDF-15 was positively linked to CACS in patients without cardiovascular disease and receiving statin therapy." (PMID 37548881, 2024). "In a cohort study of 694 smokers without clinical cardiovascular disease, the level of GDF15 in the plasma independently contributed to the risk of subclinical coronary atherosclerosis." (PMID 37093513, 2024). "The use of GDF-15, soluble ST2, and galectin-3 as diagnostic tools presents a promising strategy for the early detection of diseases, categorizing risk, and enhancing patient outcomes in various medical conditions, including cardiovascular diseases." (PMID 39328401, 2024). "GDF-15 and TIM-3 play important roles in modulating immune responses and have been implicated in various physiological and pathological processes, including inflammation, autoimmunity, cancer, and cardiovascular diseases." (PMID 39330316, 2024). "GDF-15 is the main GDF in the setting of cardiovascular disease." (PMID 37484982, 2023). "GDF-15 plays a key role in the development and progression of cardiovascular diseases." (PMID 37484982, 2023). "GDF‐15 is a stress‐responsive member of the transforming growth factor‐β cytokine superfamily and is a well‐established marker of poor prognosis and future adverse events in patients with MI but also other cardiovascular disease." (PMID 36565198, 2023). "Cardiovascular disease is also closely related to GDF‐15 production." (PMID 35334497, 2022). "In cardiovascular disease, GDF-15 is also put forward as a prognostic biomarker." (PMID 36361969, 2022). "The influence of inflammation, kidney function, cardiovascular disease, and malignancy on the expression of GDF-15 remains unknown." (PMID 34221186, 2021). "NT-proBNP is considered an indicator of myocardial necrosis and dysfunction, whereas GDF-15 is an unspecific indicator of inflammation, cellular stress and biological aging, which is elevated in cardiovascular diseases as well as in other diseases such as diabetes mellitus and renal diseases." (PMID 34834033, 2021). "Additionally, GDF-15 has been suggested as a biomarker for cardiovascular diseases, diabetes and cancer." (PMID 34571994, 2021). "Newer ones such as galectin-3, lysophosphatidylcholine, copeptin, sST2, S100B, myeloperoxidase and GDF-15 have been extensively studied in recent years as alternatives with an increased sensitivity for cardiovascular diseases, but also with significant results in the field of neurology." (PMID 34821692, 2021). "Plasma levels of GDF-15 correlated with baseline risk of cardiovascular disease but did not provide an index of risk." (PMID 33925808, 2021). "Clinical and basic investigations have indicated a significant association between circulating growth differentiation factor 15 (GDF15) and cardiovascular disease; however, the relationship between GDF15 and lower extremity atherosclerotic disease (LEAD) has been less studied." (PMID 32222153, 2020). "Higher circulating GDF-15 levels are associated with increasing cardiometabolic risk factors in individuals without the overt cardiovascular disease." (PMID 32016113, 2020). "All these data provide insight into the relationship between GDF-15 and CAD and supported that GDF-15 may be a specific marker for cardiovascular diseases, and this may be a particularly relevant pathway for inflammatory disease conditions such as CAD." (PMID 30819257, 2019). "In addition, GDF-15 has been proposed as a general predictor of cardiovascular disease also in apparently healthy women." (PMID 30645608, 2019). "Thus, circulating levels of GDF-15 have been identified as an inflammatory biomarker with prognostic value in several conditions, particularly in cardiovascular diseases." (PMID 31624933, 2019).
cardiovascular disease (continued). "The association of GDF15 with all-cause mortality was further explored in 1391 Rancho Bernardo Study participants, mean age 70 years, with no history of cardiovascular disease and followed for a mean of 11 years." (PMID 30542297, 2018). "Despite the growing body of evidence on growth differentiation factor 15 (GDF-15) reference values for patients with existing cardiovascular disease, limited investigation has been dedicated to characterizing the distribution and prognostic impact of GDF-15 in predominantly healthy populations." (PMID 29714603, 2018). "GDF15 is a prospective biomarker of cardiovascular disease (CVD)." (PMID 29967567, 2018). "Further, we analyzed the associations between GDF15 levels and the presence or absence of several risk factors for cardiovascular disease." (PMID 28798540, 2017). "GDF15 is seen as a protective cytokine against multiple stimuli in cardiovascular disease." (PMID 23799024, 2013). "GDF-15 has also been shown to be an independent prognostic information in cardiovascular disease." (PMID 23071585, 2012). "Furthermore, recent studies have reported that GDF-15 is emerging as an independent prognostic biomarker in patients with cardiovascular disease." (PMID 23071585, 2012). "Furthermore, the protective effects observed in human cardiomyocyte cell lines suggest that GDF15 may have broad applicability across different cell types, potentially extending its therapeutic relevance to other cardiovascular diseases." (PMID 41023695, 2025). "Notably, while elevated GDF15 is widely recognized as a powerful prognostic biomarker for adverse outcomes in cardiovascular diseases such as MI, a growing body of evidence indicates it also exerts direct cardioprotective effects against insults like pathological hypertrophy." (PMID 41023695, 2025). "The upregulation of GDF15 can be induced by cellular stress such as hypoxia, inflammation, and trauma, and the role of GDF15 in energy homeostasis has attracted significant attention in its potential for the treatment of cardiovascular diseases, metabolic disorders, and aging-related diseases." (PMID 38082448, 2023). "However, it’s still controversial whether GDF-15 directly contributes to the morbidity and mortality of patients suffered with cardiovascular disease (CVD)." (PMID 33115406, 2020). "GDF-15 could act as a novel biomarker in cardiovascular disease." (PMID 33201838, 2020). "Cardiovascular disease is not systematically reported in our cohort, and could potentially have biased our results due to its association with high plasma GDF-15." (PMID 30645608, 2019). "Thus, GDF15 is produced by multiple cardiovascular cell types under stressful conditions so its correlation with the well-validated cardiovascular disease risk biomarker CRP is not surprising." (PMID 29967567, 2018). "Moreover, the GDF-15 level in patients with acute coronary syndrome (ACS) was found to be independently associated with an enhanced risk of stroke and strongly correlated with an increased risk of cardiovascular disease and total mortality in ACS patients." (PMID 31435501, 2017). "However, more therapeutic intervention studies are needed to understand whether GDF-15 can be used as a prognostic marker for therapeutic intervention for different cardiovascular disorders." (PMID 26273671, 2015). "Elevated levels of GDF-15 have been associated with increased risk of diseases hypothesised to result from chronic inflammation and numerous studies showed that GDF-15 is a valuable biomarker for cardiovascular disease." (PMID 25590623, 2015). "Furthermore, in patients with CAD, GDF-15 concentrations correlated with other markers of inflammation, and elevated GDF-15 levels are now considered a strong biomarker of risk progression and mortality in cardiovascular disease." (PMID 25171167, 2014). "Recent studies have hypothesized a crucial role of the cytokine GDF-15 in cardiovascular diseases." (PMID 23800095, 2013).